IGF1R (insulin like growth factor 1 receptor)
Diseases named in the same sentence as IGF1R in open-access papers (continued):
Sharing a sentence is not in itself a finding about the gene and the disease.
prostate carcinoma (208 papers, 2005 to 2026). A carcinoma that arises from epithelial cells of the prostate gland. "HBMSC-derived extracellular vesicles were able to transfer miR-99b-5p, thereby causing the suppression of IGF1R expression in recipient prostate cancer cells." (PMID 38892104, 2024). "The EGFR/ERBB4, MET and IGF-1R families of growth factor receptor have been implicated in prostate cancer." (PMID 35954439, 2022). "A preclinical study found Cixutumumad effective against prostate cancer as it caused significant delaying of the androgen resistance by blocking IGF1R in disease." (PMID 34234737, 2021). "High levels of total IGF-1R were associated with higher tumour grade while higher levels of cytoplasmic IGF-1R were linked to a greater risk of post-radiotherapy recurrence in prostate cancer patients." (PMID 34867402, 2021). "We found that nuclear IGF-1R is more frequently detected in malignant than benign epithelium, and is associated with advanced tumour stage in prostate cancer and reduced overall survival in renal cancer." (PMID 33969359, 2021). "In prostate cancer cells nuclear IGF-1R facilitates expression of JUN and FAM 21, which are linked to cell survival, anchorage independent growth and cell migration, all of which are associated with advanced cancer stage." (PMID 33584548, 2020). "IGF1R expression in circulating tumor cells was associated with response to IGF1R targeting in patients with advanced prostate cancer." (PMID 32391121, 2020). "It has also been associated with several anti-cancer mechanisms of action in prostate cancer including inhibition of complex 1, lipogenesis, decreases of cyclin D1, down-regulation of the insulin-like growth factor 1 receptor and AR downregulation." (PMID 28151974, 2017). "The mechanisms and pathways associated with regulation of IGF1R gene expression and action in prostate cancer remain largely unidentified." (PMID 27285981, 2016). "It was previously shown that progression of prostate cancer from an organ-confined, androgen-sensitive disease to a metastatic, androgen-independent disorder is associated with a marked decrease in IGF1R expression." (PMID 27285981, 2016). "α5β1 integrin signaling is strongly interactive with IGF-1R signaling in prostate cancer cells, and IGF-1R has been shown both to associate with and enhance the stability of β1 integrin." (PMID 26191041, 2015). "IGF-1R is modified via N-linked glycosylation in prostate cancer cells and this strongly associates with the signalling activity of the receptor." (PMID 23724116, 2013). "Elevated expression of the type 1 IGF receptor (IGF-1R) is linked to radioresistance and biochemical recurrence in prostate cancer, yet the molecular mechanisms underlying IGF-1R-mediated DNA damage responses remain unclear." (PMID 42095258, 2026). "Further studies on the mechanism underlying the inhibitory effect on prostate cancer found that miR-99b-5p could bind to its downstream target insulin-like growth factor 1 receptor (IGF1R), downregulate it, and inhibit the progression of prostate cancer." (PMID 38994350, 2024). "In addition, IGF-1R is overexpressed in approximately 30% of prostate cancers and is associated with an increased risk of tumor recurrence and metastasis." (PMID 38342894, 2024). "Interestingly, high IGF-1R expression has been associated with high prostate cancer recurrence after primary radiotherapy indicating a potential role for IGF-1R for the adaptive tumor response." (PMID 35241721, 2022). "Interestingly, M1 captured that IGF1R, a gene encoding insulin-like growth factor receptor, harbored SNVs and CNVs in TCGA prostate cancer samples, and has been reported to be oncogenic genes of prostate cancer." (PMID 34131148, 2021). "Likewise, high levels of total or cytoplasmic IGF-1R expression reveal an increased risk of postradiotherapy recurrence in prostate cancer patients, indicating that radioresistance is mediated by IGF-1R." (PMID 30621219, 2019).
prostate carcinoma (continued). "Finally, an association between inhibition of the IGF-1R and suppression of the HR DNA repair pathway has been described in prostate cancer and non-small cell lung cancer cells exposed to radiation." (PMID 26510816, 2015). "Furthermore, IL6R Asp358Ala and IGF1R +3174 SNPs were significantly associated with early-onset prostate cancer, possibly due to accelerated tumor formation." (PMID 22792137, 2012). "Antibody-mediated inhibition of IGF-1R can result in significant inhibition of tumor growth in both androgen independent and dependent xenograft models and IGF-1R/EGFR crosstalk has been associated with resistance to gefitinib in the well-characterized DU145 prostate cancer cell line." (PMID 24212944, 2011). "The association between IGF-1R and prostate cancer progression is less clear." (PMID 18598360, 2008). "Previous reports have shown that GRP receptors can activate insulin-like growth factor-1 receptors (IGF-IR) leading to Akt activation in prostate cancer cells, a mechanism which may underlie bombesin-mediated cell survival." (PMID 15685238, 2005). "Targeting IGF‐1/IGF‐1R signaling has been explored as a therapeutic strategy, with IGF‐1R inhibitors showing potential in insulin‐resistant cancers, particularly in breast, colorectal, and prostate cancer." (PMID 40387523, 2025). "Research indicates that FLOT1 palmitoylation in the endoplasmic reticulum (ER) is necessary for IGF1R transport, which impacts prostate cancer cell proliferation." (PMID 40335491, 2025). "For instance, miR99b-5p is down-regulated in prostate cancer tissue, while it is up-regulated in human bone marrow mesenchymal stem cells (HBMSCs) and targets IGF1R." (PMID 38892104, 2024). "IGFBP7 merits further study as a treatment predictive biomarker in other cancer types such as colon, ovarian and prostate cancer, as well as sarcomas, where IGF-1R targeting agents have been investigated." (PMID 39362991, 2024). "At the same time, aberrant activation of the PCAT6/IGF2BP2/IGF1R axis will promote both the growth of prostate cancer and its metastasis to bone." (PMID 39771106, 2024). "In vitro, overexpression of IGF-1R in prostate cancer cell lines led to increased cell proliferation, colony formation, migration, invasion, and resistance to apoptosis, while downregulation of IGF-1R produced the opposite effects." (PMID 39638246, 2024). "Studies have shown that in prostate cancer cells with decreased expression of IGF1R, the expression of ITGB1 is also significantly decreased." (PMID 38292328, 2024). "For example, NEAT1 will facilitate prostate cancer growth by activating the IGF1R/ATK signaling pathway." (PMID 39771106, 2024). "Evaluation of IGF-1 inhibition as a novel route to radiosensitization of prostate cancers that express high total- or cytoplasmic- IGF-1R." (PMID 36831629, 2023). "In long-term DM, insulin-like growth factor 1 receptor (IGF-1R) is reduced, and elevated IGF-1 levels correlate with increased prostate cancer risk." (PMID 38034011, 2023). "Prostate cancer: insulin-deprived environment in long-term diabetes results in a lower amount of insulin-like growth factor-1 receptor (IGF-1R), and higher plasma IGF-1 is associated with a higher risk of prostate cancer." (PMID 35207564, 2022). "We previously reported that response to IGF-1R inhibition was enhanced by suppressing HR in prostate cancer models." (PMID 34773074, 2022). "Overexpression of IGF1R (insulin like growth factor 1 receptor) promotes prostate cancer growth and progression." (PMID 35317831, 2022). "High expression of PCAT6 enhanced IGF1R mRNA stability, thus contributing to prostate cancer tumorigenesis and metastasis." (PMID 36439881, 2022). "In this study, we also identified the significant correlation in co-occurrence of altered AR, IGF1R, and Wnt/β-catenin signaling pathways in both primary and advanced human prostate cancer samples." (PMID 35902588, 2022).
prostate carcinoma (continued). "First, given evidence that IGFs regulate the response to IR, we also found evidence that IGF-1R depletion induced endogenous DNA lesions marked by γH2AX foci in prostate cancer cells." (PMID 34773074, 2022). "In the future, as a more potent treatment strategy, a combination of novel IGF1R inhibitors and existing prostate cancer therapies is expected to be effective." (PMID 35370981, 2022). "IGF-1 is also implicated in castration-resistant PCa and has been shown to activate androgen receptor (AR) signaling in prostate cancer cells via the IGF-1R-forkhead box protein O1 (FOXO1) signaling axis." (PMID 35370981, 2022). "Taken together, analyses identified a new mechanism for IGF1R and AR stimulation of prostate cancer, and further support the relevance of targeting AR and IGF1R in this type of tumors with BRCA1 serving as a marker for defining the target activity." (PMID 35432218, 2022). "Emerging evidence has shown a prominent role of IGF1/IGF1R signaling activation in inducing prostate cancer development and progression in both mouse models and clinical studies." (PMID 36323713, 2022). "Upregulation of IGF1R and/or INSR constitutes a common paradigm mediating tumor resistance in different cancer types and is associated with poor prognosis in prostate cancer, squamous cell lung cancer, and prostate cancer." (PMID 34065119, 2021). "This is an interesting point when you consider that in prostate cancer it has been shown that estrogen can substitute to upregulate IGF-1R when androgen levels are low." (PMID 33816477, 2021). "PCAT6 promotes prostate cancer bone metastasis by stabilizing IGF1R mRNA through interacting with IGF2BP2." (PMID 34185427, 2021). "The authors identified IGF1R binding on the jun and fam21 promoters in fresh prostate cancer samples containing abundant nuclear IGF1R." (PMID 33918477, 2021). "In prostate cancer cells androgens have been shown to upregulate the expression of IGF-1R and as a consequence results in increased proliferation and invasion when stimulated with IGF-1." (PMID 33816477, 2021). "These functions have an effect on cancer cells, as AP2M1 regulates insulin-like growth factor-1 receptor (IGF1R) in prostate cancer and EGFR internalization in bladder cancer." (PMID 34565296, 2021). "On the other hand, IGF1R usually co-expressed with androgen receptor in response to dihydrotestosterone (a male-sex hormone)-dependent prostate cancer cell proliferation." (PMID 32150843, 2020). "Let-7a down regulates the IGF-1R by targeting the 3’UTR of IGF-1R mRNA and is accompanied by suppression of Elk1 and c-fos, leading to growth inhibition of prostate cancer." (PMID 31847392, 2019). "A close crosstalk exists between IGF1R and androgen receptor (AR), a transcription factor acting as a driver in prostate cancer." (PMID 29462882, 2018). "AR stimulation increases IGF1R expression in prostate cancer cells and hexosamine production, resulting in increased N- and O-glycosylation." (PMID 29462882, 2018). "In prostate cancer cells, androgen receptor and IGF1R form a feedback loop in which AR activates IGF1R, which, in turn, stimulates AR activity." (PMID 29462882, 2018). "Previously studies discovered that inhibition of IGF-1R protein levels is a prime element for suppressing prostate cancer progression via inhibition of angiogenesis and metastasis in the TRAMP mouse model." (PMID 30250021, 2018). "The result significantly indicated the harmful effect of IGF-1R inhibitors to treat prostate cancer." (PMID 28427155, 2017). "The invasive and migratory potential of prostate cancer cells is also decreased by metformin in prostate cancer cell via the impairment of the insulin-like growth factor 1 receptor (IGF-1R) axis." (PMID 27164115, 2016).
prostate carcinoma (continued). "Transactivation of the IGF1R gene by oncogene ERG constitutes a key event in prostate cancer development." (PMID 27285981, 2016). "We demonstrated that basal and phosphorylated IGF1R levels progressively decreased as prostate cancer cells became more tumorigenic and metastatic." (PMID 27285981, 2016). "In conclusion, our results demonstrate that the IGF1R gene is a biologically relevant target for a novel family of prostate cancer-specific chimeric proteins." (PMID 27285981, 2016). "Transcriptional regulation of the IGF1R gene by ER and AR is of major importance in the etiology of breast and prostate cancers, respectively." (PMID 27446805, 2016). "The important role of IGF1R in prostate cancer initiation and progression has been well established." (PMID 27285981, 2016). "Prominent IGF-1R nuclear positivity in the tumor of our patient is of interest, given our previous finding that nuclear IGF-1R in prostate cancer models is induced by ligand and blocked by IGF-1R kinase inhibition." (PMID 27200287, 2016). "In PC-3 xenograft models of human prostate carcinoma, tumor growth is suppressed via the impaired transcription of the gene coding for IGF-1R." (PMID 27164115, 2016). "Combined, we provided evidence that activated wild type AR enhances IGF1R transcription in prostate cancer cells via a mechanism that involves AR binding to the IGF1R promoter." (PMID 27285981, 2016). "Sp1 was identified as a cardinal transactivator of the IGF1R gene in different tumor types, including prostate cancer." (PMID 27285981, 2016). "The insulin-like growth factor-1 receptor (IGF1R) plays a key role in cell growth and tumorigenesis, and is overexpressed in most malignancies, including prostate cancer." (PMID 27285981, 2016). "The present study identifies the IGF1R gene as a novel downstream target for the TMPRSS2-ERG fusion protein in prostate cancer." (PMID 27285981, 2016). "In prostate cancer cells, co-inhibition of epidermal growth factor receptor and IGF-1R reduced phosphorylation of IRS-1 and its interaction with RAD51, suppressing HR and increasing radio-sensitivity." (PMID 26510816, 2015). "Work by Aleksic and colleagues showed that IGF-1 can stimulate ligand-dependent internalization and nuclear translocation of full-length IGF-1R subunits in prostate cancer cells." (PMID 26217584, 2015). "Previous studies have shown that IGF-1/IGF1R activation can promote EMT in prostate cancer cells and human mammary epithelial cells." (PMID 26554308, 2015). "Metformin inhibited prostate cancer proliferation through abrogating androgen-induced IGF-1R expression which is partially dependant on AMPK activation." (PMID 26492952, 2015). "We have recently described a novel mechanism of cross-talk between estrogens and IGF system in prostate cancer cells, involving the upregulation of the IGF-1R through the classical ERs acting via MISS." (PMID 25798130, 2015). "So far, IGF-1, IGF-1R, and IGFBP3 levels have only been shown to be possible but deficient prostate cancer risk markers." (PMID 24877145, 2014). "We have shown that a PNA targeted to the coding region of IGF-1R mRNA inhibits translation elongation and cell transformation when introduced by electroporation to human prostate cancer cells grown in culture." (PMID 25127364, 2014). "The interplay between IGF1R and the androgen receptor (AR) was mainly investigated in prostate cancer models." (PMID 24904527, 2014). "Of interest, a recent study demonstrated that metformin inhibits IGF1R up-regulation in prostate cancer cells via a mechanism that involves disruption of membrane-initiated androgen signaling." (PMID 24904527, 2014). "We recently published that dietary fat reduction combined with IGF-1R antibody blockade resulted in decreased proliferation in prostate cancer xenografts and a reduction in serum insulin and TNF alpha levels without affecting final tumor weights." (PMID 23823800, 2013).
prostate carcinoma (continued). "AR itself can activate IGF-1R expression and IGF-1R stimulates AR activity in prostate cancer cells." (PMID 23724116, 2013). "In summary, calorie restriction alone and in combination with IGF-1R antibody blockade resulted in decreased growth of prostate cancer xenografts." (PMID 23823800, 2013). "IGF-1R isup-regulated in prostate cancer and is knownto be up-regulated atthe mRNA and protein levels by androgen stimulation." (PMID 23724116, 2013). "In a pre-clinical study, the IMC-A12 anti-IGF-1R antibody (ImClone Systems Incorporated, Somerville, NJ, USA) decreased LuCAP prostate cancer xenograft growth." (PMID 23823800, 2013). "The SNPs in LEPR Gln223Arg, SPP1-66 T>G, IGF1R+3174 G>A, IGFBP3-202 A>C, FGF2+223 C>T and IL6-597 G>A, plus age and PSA remained independently associated with risk for overall, and for high-grade prostate cancer." (PMID 22792137, 2012). "Several growth factor receptors including the epidermal growth factor receptor (EGFR) and insulin-like growth factor-1 receptor (IGF-1R) have been shown to be overexpressed in prostate cancer." (PMID 22454635, 2012). "Not surprisingly, without significant response rates observed for common cancers (i.e., breast, colon, lung, or prostate cancer), many pharmaceutical companies have ceased, or at a minimum delayed, clinical development of their respective IGF-1R inhibitors." (PMID 24212944, 2011). "Overexpression of insulin-like growth factor 1 receptor (IGF-1R) has been observed in many prostate cancers and, in particular, it is upregulated in vivo during the progression to castration resistance." (PMID 24212771, 2011). "In this regard, in PC-3 prostate cancer cells, IGF-1R signaling has been shown to be attenuated by rosiglitazone via non-genomic action on ERK 1/2, and protein kinase AKT phosphorylation." (PMID 19587804, 2009). "The IGF-1/IGF-1R axis is well known to contribute to prostate cancer initiation, but its contribution to invasiveness and the downstream signalling mechanisms that are involved are unclear at present." (PMID 18598360, 2008). "Targeting of IGF-1R signalling in preclinical tumour models has suppressed growth of prostate cancer cells, induced apoptosis in vitro and in vivo and has sensitised cancer cells to conventional chemotherapeutic treatment and irradiation." (PMID 16983403, 2006). "Nuclear insulin‐like growth factor‐1 receptor (IGF‐1R) undergoes IGF‐induced recruitment to cancer cell chromatin in vitro and associates with advanced prostate cancer (PCa) stage in clinical tissue, prompting this investigation of IGF‐1R chromatin recruitment in vivo." (PMID 41028981, 2025). "Furthermore, antrocin, another bioactive constituent of AC, has been found to enhance the sensitivity of prostate cancer cells to radiation therapy by targeting downstream IGF-1R signaling pathways." (PMID 40141325, 2025). "Both epidemiological and experimental studies have confirmed that IGF-1R expression in tumor tissue is significantly higher than in normal tissue, and its high expression is closely related to the aggressiveness and lethality of prostate cancer." (PMID 41584612, 2025). "Moreover, the abnormal expression of IGF1R out of regulation will contribute to the invasion of prostate cancer." (PMID 39771106, 2024). "Additionally, we identified five downstream genes (IGF1R, BMI1, RHAMM, NuSAP1, and PBK) of E2F1 in prostate cancer, and these genes are associated with the survival and proliferation of prostate cancer." (PMID 38374143, 2024). "In addition, DeRita and colleagues demonstrated that a variety of prostate cancer cell lines display enrichment of IGF1R, c-Src, and active SrcpY416 in extracellular vesicles." (PMID 38892104, 2024). "IGF-1R has been reported to activate MET in prostate cancer cells." (PMID 38439082, 2024).